PADI4 (peptidyl arginine deiminase 4)
Description:
Catalyzes the citrullination/deimination of arginine residues of proteins such as histones, thereby playing a key role in histone code and regulation of stem cell maintenance. Citrullinates histone H1 at 'Arg-54' (to form H1R54ci), histone H3 at 'Arg-2', 'Arg-8', 'Arg-17' and/or 'Arg-26' (to form H3R2ci, H3R8ci, H3R17ci, H3R26ci, respectively) and histone H4 at 'Arg-3' (to form H4R3ci). Acts as a key regulator of stem cell maintenance by mediating citrullination of histone H1: citrullination of 'Arg-54' of histone H1 (H1R54ci) results in H1 displacement from chromatin and global chromatin decondensation, thereby promoting pluripotency and stem cell maintenance. Promotes profound chromatin decondensation during the innate immune response to infection in neutrophils by mediating formation of H1R54ci. Citrullination of histone H3 prevents their methylation by CARM1 and HRMT1L2/PRMT1 and represses transcription. Involved for the formation of neutrophil extracellular traps (NETs) by mediating citrullination of histone H3 and initiating decondensation of chromatin and nuclear membrane rupture. NETs are mainly composed of DNA fibers and are released by neutrophils to trap pathogens during inflammation. Citrullinates EP300/P300 at 'Arg-2142', which favors its interaction with NCOA2/GRIP1.
Synonyms: PAD4; PADI5; PDI5; PAD; PDI4
Tractability: Small molecule: a structure with a bound ligand is known; a high-quality ligand is known; it has a high-quality binding pocket. PROTAC: a small molecule that binds it is known.
Target class: Enzyme
Chemical probes: GSK484 (high quality), ML325
Gene: Protein-coding gene on chromosome 1 (17,308,195 to 17,364,004, forward strand). Ensembl gene ENSG00000159339.
Subcellular location: Cytoplasm; Nucleus; Cytoplasmic granule
Pathways (Reactome):
Chromatin organization: Chromatin modifying enzymes
Gene Ontology:
Molecular function: calcium ion binding; histone arginine deiminase activity; histone H3R17 arginine deiminase activity; histone H3R2 arginine deiminase activity; histone H3R26 arginine deiminase activity; histone H3R8 arginine deiminase activity; identical protein binding; protein binding; protein-arginine deiminase activity
Biological process: negative regulation of heterochromatin formation; neutrophil extracellular trap formation; nuclear membrane disassembly; post-translational protein modification; chromatin organization; chromatin remodeling; nucleosome assembly; protein modification process; stem cell population maintenance
Cellular component: cytoplasm; nucleus; protein-containing complex; cytosol; nucleoplasm
Genetic constraint (gnomAD): Loss-of-function variants: 37 observed, 48.08 expected, observed/expected ratio (o/e) 0.77, 90% interval 0.59 to 1.01. The upper end of that interval is the gene's LOEUF score, 1.01, which puts it in group 4 of 6, group 1 being the genes least tolerant of losing a copy. Missense variants: 702 observed, 720.9 expected, observed/expected ratio (o/e) 0.97, 90% interval 0.91 to 1.04. Synonymous variants: 305 observed, 306.83 expected, observed/expected ratio (o/e) 0.99, 90% interval 0.9 to 1.09.
Homologues: Orthologues: chimpanzee PADI4 (99% identical), macaque PADI4 (94% identical), guinea pig PADI4 (77% identical), pig PADI4 (77% identical), mouse Padi4 (73% identical), rat Padi4 (72% identical), dog PADI4 (65% identical), zebrafish padi2 (45% identical). Paralogues in human: PADI1 (57% identical), PADI3 (56% identical), PADI2 (50% identical), PADI6 (46% identical).
Diseases named in the same sentence as PADI4 in open-access papers:
PADI4 is named in the same sentence as 268 diseases in open-access papers, as found by Europe PMC text mining. Sharing a sentence is not in itself a finding about the gene and the disease. The quoted sentences say what the papers report.
rheumatoid arthritis (125 papers, 2006 to 2026). A chronic, systemic autoimmune disorder characterized by inflammation in the synovial membranes and articular surfaces. "The same group of scientists revealed that the allele at rs2240335 within PADI4 affects rheumatoid arthritis susceptibility by increased expression of PADI4 in neutrophils but reduced in monocytes." (PMID 38745328, 2024). "Peptidyl arginine deiminase 4 (PADI4) has been implicated in Rheumatoid arthritis (RA) pathogenesis." (PMID 37193992, 2023). "Variants unique to a specific autoimmune disease such as those in PADI2 and PADI4 that are associated with rheumatoid arthritis are also discussed, addressing their role in disease-specific immunopathology." (PMID 35979360, 2022). "Genetic variation in PADI4 has been associated with rheumatoid arthritis through the utilization of GWAS." (PMID 34573423, 2021). "In the case of lupus, the authors studied nine single nucleotide polymorphisms (initially described as haplotypes associated with rheumatoid arthritis), located all along the PADI4 gene, in the coding or non-coding regions." (PMID 33228136, 2020). "We demonstrate that rs2240335 in PADI4 correlates with reduced anti-histone antibodies and increased rheumatoid arthritis risk in North Americans." (PMID 31242568, 2019). "For rheumatoid arthritis a positive correlation between SNPs of the PADI4 gene and the susceptibility for and severity of the disease has been described." (PMID 31349745, 2019). "These PADI4 SNPs are associated with diseases e.g., rheumatoid arthritis, lupus, Alzheimer’s disease, ulcerative colitis, multiple sclerosis, and certain cancers." (PMID 31349745, 2019). "Here, we determine if single nucleotide polymorphism rs2240335 in PADI4, whose G allele is associated with reduced PAD4 in neutrophils, correlates with NETs, anti-histone antibodies, and rheumatoid arthritis susceptibility in North Americans." (PMID 31242568, 2019). "Hashemi et al20 showed that PADI4 rs1748033 gene polymorphism increased the risk of rheumatoid arthritis in a sample of the Iranian population." (PMID 30044533, 2018). "Many studies have evaluated the correlation between peptidylarginine deiminase 4 (PADI4) -92C/G polymorphism and rheumatoid arthritis (RA), but the results remain inconclusive." (PMID 28832760, 2017). "Many studies have also reported that genetic variants in the PADI4 locus are related to rheumatoid arthritis." (PMID 27556695, 2016). "rs74058715-T, a nearby SNP independent to rs2240335 (r2=0.02), is associated with reduced PADI4 expression in both cell types providing an additional instrument to probe the role of PADI4 in neutrophils in rheumatoid arthritis risk." (PMID 26151758, 2015). "First, we show how integration of neutrophil and monocyte eQTL and epigenetic data with genome-wide association study (GWAS) data implicates PADI4 expression in neutrophils in rheumatoid arthritis susceptibility." (PMID 26151758, 2015). "Four SNPs (single nucleotide polymorphisms) have been described in PADI4 gene to form a susceptibility haplotype for rheumatoid arthritis (RA); nevertheless, results in association studies appear contradictory in different populations." (PMID 24454473, 2013). "Further evidence has confirmed that PADI4 is significantly associated with rheumatoid arthritis (RA), thus playing an important role in the pathogenesis of this disease." (PMID 19183436, 2009). "Of the five PADI isoforms, PADI2 and PADI4 are the most studied, and the excessive citrullination of target proteins by their abnormal enzyme activity is one of the main causes of some diseases, such as rheumatoid arthritis (RA) and many cancer types." (PMID 35218410, 2022). "While an increased PADI4 expression in bronchoalveolar lavage fluid in smokers with rheumatoid arthritis-associated interstitial lung disease argues for it, the missing link to the citrullinated auto-antibodies confirming PADI4 activity in these patients argues against it." (PMID 36552632, 2022).
rheumatoid arthritis (continued). "The PADI4 gene is located on the short arm of chromosome 1 at position 36.13 and functional polymorphisms, such as rs11203366, rs2240340 and rs1748033 have been associated with susceptibility to rheumatoid arthritis in different populations." (PMID 30044533, 2018). "However, the majority of these studies evaluated the relationship between PADI4 gene polymorphisms with rheumatoid arthritis development." (PMID 30044533, 2018). "This study aimed to investigate the associations of PTPN22 and PADI4 gene polymorphisms with rheumatoid arthritis (RA) susceptibility and disease activity in the Aswan population." (PMID 40983977, 2025). "The Padi4 gene falls within a susceptibility locus for Rheumatoid Arthritis (RA), and certain single nucleotide polymorphisms are associated with the disease." (PMID 35706669, 2022). "Many studies have analyzed the association between peptidylarginine deiminase 4 (PADI4) -104C/T polymorphism and rheumatoid arthritis (RA)." (PMID 29518108, 2018). "Many studies have reported that both a ‘shared epitope’ (SE) encoded by several HLA-DRB1 alleles and the peptidyl arginine deiminase type 4 (PADI4) gene polymorphisms are associated with susceptibility to rheumatoid arthritis (RA)." (PMID 28182665, 2017). "Peptidylarginine deiminase type 4 (PADI4) has been identified as a susceptibility gene for rheumatoid arthritis (RA) by genome-wide association studies." (PMID 27150598, 2016). "A synonymous exonic SNP rs2240335 (PADI4 gene) has been associated to Rheumatoid Arthritis (RA) in a previous GWAS (P-value = 2E-8) using a Japanese cohort (1247 RA cases and 1486 controls)." (PMID 23844243, 2013). "Citrullinated peptides can act as autoantigens thereby increasing the risk of rheumatoid arthritis (RA), as such, PADI4 gene expression has been detected in the synovial tissue from RA patients." (PMID 21354348, 2011). "Peptidylarginine deiminase type 4 (PADI4) genotypes were shown to influence susceptibility to rheumatoid arthritis (RA) in the Japanese population." (PMID 16469113, 2006). "Among differentially expressed proteins for the mild degeneration group, we found for example PADI4, which has previously been studied regarding rheumatoid arthritis (RA), but has also been detected in synovial membrane in regard to OA." (PMID 38750696, 2024). "Rheumatoid arthritis (RA) is the most well-known autoimmune disease connected with PADI4, the gene encoding human PAD4 protein." (PMID 36823444, 2023). "In PADI4, the genotypes rs11203366-AA, rs11203367-CC, and rs874881-GG were associated with a susceptibility to interstitial lung disease in individuals with rheumatoid arthritis and rs1748033-T with a susceptibility to RA in comparison with CHS subjects." (PMID 37759458, 2023). "Most pertinently, significant efforts are currently underway to develop PADI4 inhibitors for the treatment of rheumatoid arthritis, systemic lupus erythematosus, atherosclerosis, thrombosis, sepsis, irritable bowel syndrome, and colon cancer." (PMID 35603697, 2022). "In rheumatoid arthritis (RA), PADI4 increases thrombin activity by citrullinating antithrombin, and thereby affects the vascular endothelial cells proliferation and RA synovial tissue inflammation." (PMID 35045833, 2022). "In 2003, Kazukiho Yamamoto’s team provided the first demonstration of a genetic link between PADI4 haplotypes and the severe autoimmune disease, rheumatoid arthritis." (PMID 33228136, 2020). "Genome-wide association studies have identified several single nucleotide polymorphisms (SNPs) in PADI4, the gene encoding PAD4, that are associated with rheumatoid arthritis." (PMID 31242568, 2019). "With specific high expression in blood lymphocytes, PADI4 is believed to be an active autoimmune player in synovial tissue of rheumatoid arthritis." (PMID 29915691, 2018). "We further demonstrate how eQTL in PADI4 and NOD2 delineate risk variant function in rheumatoid arthritis, leprosy and Crohn’s disease." (PMID 26151758, 2015).
rheumatoid arthritis (continued). "Peptidyl arginine deiminase 4 (PAD4) is an enzyme that is involved in protein citrullination, and is a target for anti-citrullinated peptide antibodies (ACPAs) in rheumatoid arthritis (RA)." (PMID 26293116, 2015). "A study similar to ours showed the same distribution of the IgG subclass response to a self-antigen, peptidylarginine deiminase 4 (PADI4), in patients with rheumatoid arthritis (RA)." (PMID 23705835, 2013). "In the present study, we found that PADI4 risk allele and HLA-DRB1 shared epitope are independent genetic risks for radiographic progression in Japanese rheumatoid arthritis patients." (PMID 23577190, 2013). "Wild-type mice, CA1-Tg treated with bovine serum albumin (BSA) and transgenic mice over-expressing PADI4 (PADI4-Tg), a gene known to be involved in rheumatoid arthritis, were used as controls." (PMID 23256642, 2012). "In rheumatoid arthritis (RA), the GTG haplotype [SNPs 89G/A (rs11203366), 90T/C (rs11203367), and 92G/C (rs874881)] of the PADI4 gene confers susceptibility for presenting the disease, and higher levels of PADI4 mRNA." (PMID 38524554, 2024). "One possible explanation for this contradictory observation might be the increased levels of anti-PADI4 antibodies found in blood of smokers with rheumatoid arthritis." (PMID 36552632, 2022). "Peptidylarginine deiminase 4 (PADI4), which encodes PAD4, was initially identified as a non-HLA susceptibility gene in rheumatoid arthritis." (PMID 32655553, 2020). "AutoAbs targeting cyclic citrullinated peptide and PADI4 are prevalent in rheumatoid arthritis." (PMID 31494269, 2019). "These structural and biochemical analyses suggest that improper protein citrullination in rheumatoid arthritis patients is not caused by defects in citrullination activity but by other reasons such as enhanced PADI4 mRNA stability." (PMID 27556695, 2016). "PTPN22, PADI-4, and CTLA-4 have been associated with risk for rheumatoid arthritis (RA)." (PMID 18462498, 2008). "Rheumatoid arthritis (RA) susceptibility is influenced by genetic polymorphisms such as PTPN22 and PADI4, though their associations vary significantly across ethnic populations." (PMID 40983977, 2025). "Furthermore, citrullination by peptidyl arginine deiminase 4 (PAD4) not only modifies histones but may also trigger the formation of autoantibodies, exacerbating autoimmune conditions such as rheumatoid arthritis and systemic lupus erythematosus." (PMID 39201339, 2024). "Some evidence indicates the presence of GB-derived rheumatoid arthritis autoantigens; specifically, peptidyl arginine deiminase 4 (PAD4) was able to promote enhanced stimulation of autoreactive T cells, thus contributing to rheumatoid arthritis pathogenesis." (PMID 38646541, 2024). "We aimed to identify the relationship between polymorphisms in PADI2 and PADI4 in developing interstitial lung disease in patients with rheumatoid arthritis, their correlation with the PAD2, PAD4 protein levels, and clinical characteristics in RA-ILD." (PMID 37759458, 2023). "ELISA is not a substitute for PCR in directly genotyping PTPN22 or PADI4, but it is useful in rheumatoid arthritis (RA) research." (PMID 40983977, 2025). "PADI4 is a type of PAD enzyme found in different cells, such as breast cancer cells, leukocytes, and embryonic stem cells and is involved in cancer etiology and rheumatoid arthritis." (PMID 39315094, 2024). "In contrast to rheumatoid arthritis, the readout for PADI4 activity during wound healing is not the formation of citrullinated auto-antibodies but the formation of NETs." (PMID 36552632, 2022). "Quantitative proteomics analysis of NETs in response to PMA and A23187 in neutrophils from rheumatoid arthritis and SLE indicated PMA-induced NETs contained proteins of annexin family, azurocidin, and histone H3, whereas A23187 enriched CAMP/LL37, CRISP3, lipocalin, IL-8, and PADI4." (PMID 35622142, 2022).
rheumatoid arthritis (continued). "A total of 320 SNPs from the PADI locus (including PADI1, PADI2, PADI3, PADI4 and PADI6 genes) were genotyped in 1,238 RA cases and 1,571 control subjects from the Malaysian Epidemiological Investigation of Rheumatoid Arthritis (MyEIRA) case-control study." (PMID 23164236, 2012).
Sepsis (76 papers, 2012 to 2026). Sepsis is defined as life-threatening organ dysfunction caused by a dysregulated host response to infection. "Concurrently, C10 IMs also increased after sepsis (0.4% in WT Sham versus 39.1% in WT PA), with a subsequent decreased level observed following Padi2 and Padi4 deficiency (39.1% in WT PA versus 18.7% in DKO PA)." (PMID 39405117, 2024). "Deletion of Padi2 enhances survival and diminishes lung injury in sepsis, while Padi4 deficiency benefits the LPS-induced endotoxic shock model but not in cecal ligation and puncture (CLP) or pneumonia models." (PMID 39405117, 2024). "In diabetics, delayed wound healing and infections/sepsis are associated with increased neutrophilic PADI4 expression and formation of neutrophil extracellular traps (NETs)." (PMID 36552632, 2022). "Padi2 and Padi4 deficiency reduces ALI in a PA pneumonia–induced sepsis mouse model." (PMID 39405117, 2024). "Neutrophils contribute to NET formation, with NETosis regulated by proteins such as peptidylarginine deiminase I4 (PADI4), which plays a role in both immune responses and coagulation during sepsis-related immunothrombosis." (PMID 40649892, 2025). "Gene expression profiling has identified several NET-related genes—ELANE, TLR4, MPO, PADI4, CTSG, MMP9, and S100A12—as being potential diagnostic biomarkers and therapeutic targets for sepsis." (PMID 40806591, 2025). "Our research aimed to elucidate how Padi2 and Padi4 deletions affect these mechanisms, revealing that such deletions enhance survival rates and mitigate lung injury in a PA pneumonia–induced sepsis mouse model." (PMID 39405117, 2024). "Among the 5 related calcium-dependent PADI isoforms, PADI2 and PADI4 are highly expressed in monocytes and macrophages, and they play substantial roles in the immune response to sepsis." (PMID 39405117, 2024). "This study investigated the roles of PADI2 and PADI4 enzymes in regulating the immune response during sepsis, particularly focusing on their influence on the critical balance between proinflammatory and antiinflammatory pathways." (PMID 39405117, 2024). "Padi2 and Padi4 deletion led to an increase in mature AMs after PA infection, potentially improving bacterial clearance and reducing sepsis-induced ALI." (PMID 39405117, 2024). "Intriguingly, the deletion of Padi2 and Padi4 modulated this myeloid-macrophage differentiation and polarization, consequently altering the inflammatory milieu within the lung after sepsis." (PMID 39405117, 2024). "As a result, PADI4 inhibition has been studied extensively as an approach to alleviate NET-associated pathologies that manifest in diabetes, sepsis, infection-induced lung injury, age-related cardiac fibrosis, deep-vein thrombosis and myocardial ischemia." (PMID 35706669, 2022). "In diabetics, increased neutrophilic PADI4 expression and related excessive NET formation have been linked to delayed wound healing and/or infections/sepsis." (PMID 36552632, 2022). "In addition, several drugs have been reported to attenuate NET-driven thrombosis in sepsis by inhibiting PADI4 or by reducing NETosis through CXCR1/2 antagonism." (PMID 40649892, 2025). "Considering the potential critical roles of both PADI2 and PADI4 in sepsis, we hypothesize that the deletion of both Padi2 and Padi4 could offer a marked therapeutic advantage." (PMID 39405117, 2024). "Peptidyl arginine deiminase 2 (PADI2) and PADI4 play crucial roles in mediating the host’s immune response in sepsis, but their specific functions remain unclear." (PMID 39405117, 2024). "Blocking the formation of NETs by peptidyl arginine deiminase 4 (PAD4) inhibitor and PAD4 knockdown in mice, or inducing the depletion or degradation of NETs by anti-Ly6G and DNase, can significantly reduce sepsis-induced ferroptosis and protect mice from SA-AKI." (PMID 36505499, 2022). "The authors conclude against a role of PADI4 in the pathogenesis of sepsis." (PMID 31416265, 2019).